ZC3H7B (zinc finger CCCH-type containing 7B)
Description:
May be a specific regulator of miRNA biogenesis. Binds to microRNAs MIR7-1, MIR16-2 and MIR29A hairpins recognizing the 'ATA(A/T)' motif in the apical loop.
Synonyms: RoXaN; KIAA1031; FLJ13787; DKFZp434K0920; ROXAN1
Tractability: PROTAC: ubiquitination databases record sites on it; its protein half-life has been measured.
Gene: Protein-coding gene on chromosome 22 (41,301,457 to 41,360,155, forward strand). Ensembl gene ENSG00000100403.
Subcellular location: Nucleus
Subcellular location (Human Protein Atlas): Cytosol
Gene Ontology:
Molecular function: miRNA binding; protein binding; RNA binding; metal ion binding
Biological process: miRNA processing; post-transcriptional regulation of gene expression
Cellular component: nucleus
Genetic constraint (gnomAD): Loss-of-function variants: 36 observed, 118.61 expected, observed/expected ratio (o/e) 0.3, 90% interval 0.23 to 0.4. The upper end of that interval is the gene's LOEUF score, 0.4, which puts it in group 1 of 6, group 1 being the genes least tolerant of losing a copy. Missense variants: 1,001 observed, 1,343.8 expected, observed/expected ratio (o/e) 0.74, 90% interval 0.71 to 0.79. Synonymous variants: 498 observed, 561.53 expected, observed/expected ratio (o/e) 0.89, 90% interval 0.82 to 0.95.
Homologues: Orthologues: macaque ZC3H7B (98% identical), guinea pig ZC3H7B (97% identical), rabbit ZC3H7B (97% identical), chimpanzee ZC3H7B (96% identical), dog ZC3H7B (96% identical), mouse Zc3h7b (96% identical), pig ZC3H7B (96% identical), rat Zc3h7b (96% identical), tropical clawed frog zc3h7b (53% identical), zebrafish zc3h7bb (40% identical), zebrafish zc3h7ba (39% identical). Paralogues in human: ZC3H7A (46% identical).
Diseases named in the same sentence as ZC3H7B in open-access papers:
ZC3H7B is named in the same sentence as 10 diseases in open-access papers, as found by Europe PMC text mining. Sharing a sentence is not in itself a finding about the gene and the disease. The quoted sentences say what the papers report.
depression (2 papers, 2021 to 2023). "In a meta-analysis of a genome-wide association study of depression, it was found that the differential expression of ZC3H7B in three included studies was highly consistent, indicating that this gene may be related to depression." (PMID 36911124, 2023).
sarcoma (2 papers, 2021 to 2025). A usually aggressive malignant neoplasm of the soft tissue or bone. "BCOR-rearranged sarcomas comprise sarcomas with BCOR–CCNB3, BCOR–MAML3 and ZC3H7B–BCOR fusions, and sarcomas with BCOR internal duplications." (PMID 33919988, 2021).
endometrial stromal sarcomas (1 paper, 2020). "In contrast, high-grade endometrial stromal sarcomas (HG-ESSs) have been found to harbor YWHAE-NUTM2A/B or ZC3H7B-BCOR fusion genes and to exhibit more aggressive behavior." (PMID 32921307, 2020).
gastric cancer (1 paper, 2022). A primary or metastatic malignant neoplasm involving the stomach. "Four genes, RBM15, FTO, MSI2 and ZC3H7B were identified as influencing the prognosis of gastric cancer patients in univariate analysis of 24 regulators." (PMID 36003776, 2022).
ossifying fibromyxoid tumor (1 paper, 2024). A rare soft tissue tumor of uncertain lineage characterized by the presence of neoplastic spindle to round cells forming cords in a fibromyxoid stroma. "Furthermore, the connection between LGG and ZC3H7B, a gene that encodes a protein linked to ossifying fibromyxoid tumors and myxoid leiomyosarcoma, has yet to be investigated." (PMID 38173044, 2024).
virus infection (1 paper, 2022). "Besides, potential HDAC3 deacetylation targets also involved few RNA-binding proteins, including for example ZC3H7B, which plays a role during virus infection." (PMID 35994477, 2022).
tumor (5 papers, 2022 to 2025). "Recent studies have found that the molecular characteristics of HGESS (such as gene fusions like YWHAE-NUTM2, ZC3H7B-BCOR, etc.)drive the high invasiveness of the tumor." (PMID 40977714, 2025). "Recently, various new fusion partners of BCOR have been documented, such as MAML3, ZC3H7B, RGAG1, and KMT2D, further increasing the complexity of such tumor entities, although the molecular pathogenetic mechanism remains to be elucidated." (PMID 36765856, 2023).
cancer (1 paper, 2022). A tumor composed of atypical neoplastic, often pleomorphic cells that invade other tissues. "Among them, TNRC6, DGCR8, C17ORF85, ZC3H7B, SFRS1 and TIA1, were obviously positively associated with XIST in ≥3 cancers; while eIF4AIII, FXR1, FXR2 and C22ORF28 were significantly negatively correlated with XIST in ≥3 cancers." (PMID 36212008, 2022).
ZC3H7B also shares sentences with these, for which no sentence is quoted: breast tumors (1 paper); schizophrenia (1).